JAK3 (Janus kinase 3)
Description:
Non-receptor tyrosine kinase involved in various processes such as cell growth, development, or differentiation. Mediates essential signaling events in both innate and adaptive immunity and plays a crucial role in hematopoiesis during T-cells development. In the cytoplasm, plays a pivotal role in signal transduction via its association with type I receptors sharing the common subunit gamma such as IL2R, IL4R, IL7R, IL9R, IL15R and IL21R. Following ligand binding to cell surface receptors, phosphorylates specific tyrosine residues on the cytoplasmic tails of the receptor, creating docking sites for STATs proteins. Subsequently, phosphorylates the STATs proteins once they are recruited to the receptor. Phosphorylated STATs then form homodimer or heterodimers and translocate to the nucleus to activate gene transcription. For example, upon IL2R activation by IL2, JAK1 and JAK3 molecules bind to IL2R beta (IL2RB) and gamma chain (IL2RG) subunits inducing the tyrosine phosphorylation of both receptor subunits on their cytoplasmic domain. Then, STAT5A and STAT5B are recruited, phosphorylated and activated by JAK1 and JAK3. Once activated, dimerized STAT5 translocates to the nucleus and promotes the transcription of specific target genes in a cytokine-specific fashion.
Synonyms: JAK-3; L-JAK; JAKL; LJAK; JAK3_HUMAN
Tractability: Small molecule: an approved drug acts on it; a structure with a bound ligand is known; a high-quality ligand is known; it has a high-quality binding pocket; it belongs to a druggable protein family. Antibody: its Gene Ontology location is reachable by antibodies, with high confidence; UniProt places it where antibodies can reach, with medium confidence; the Human Protein Atlas places it where antibodies can reach. PROTAC: it is named in the literature on targeted protein degradation; ubiquitination databases record sites on it; its protein half-life has been measured; a small molecule that binds it is known.
Target class: TK protein kinase group; Enzyme; Kinase; Protein Kinase; Tyrosine protein kinase JakA family
Chemical probes: FM-381 (high quality), FM-409 (high quality), JAK3-IN-14, JAK3i, PD084641, PF-06263276, TL6-144 (high quality), tofacitinib (high quality)
Gene: Protein-coding gene on chromosome 19 (17,824,780 to 17,848,071, reverse strand). Ensembl gene ENSG00000105639.
Subcellular location: Endomembrane system; Cytoplasm
Subcellular location (Human Protein Atlas): Cytosol; Plasma membrane
Pathways (Reactome):
Immune System: Interleukin receptor SHC signaling; Interleukin-15 signaling; Interleukin-2 signaling; Interleukin-20 family signaling; Interleukin-21 signaling; Interleukin-4 and Interleukin-13 signaling; Interleukin-7 signaling; Interleukin-9 signaling
Signal Transduction: RAF/MAP kinase cascade; Signaling by ALK
Disease: Potential therapeutics for SARS
Gene Ontology:
Molecular function: protein binding; protein phosphatase binding; protein tyrosine kinase activity; growth hormone receptor binding; non-membrane spanning protein tyrosine kinase activity; ATP binding; protein kinase activity
Biological process: interleukin-15-mediated signaling pathway; interleukin-2-mediated signaling pathway; interleukin-4-mediated signaling pathway; interleukin-7-mediated signaling pathway; interleukin-9-mediated signaling pathway; negative regulation of T-helper 17 cell lineage commitment; response to interleukin-4; B cell differentiation; cell differentiation; cell surface receptor signaling pathway via JAK-STAT; cytokine-mediated signaling pathway; enzyme-linked receptor protein signaling pathway; growth hormone receptor signaling pathway via JAK-STAT; intracellular signal transduction; negative regulation of dendritic cell cytokine production; negative regulation of glycoprotein biosynthetic process; negative regulation of interleukin-10 production; negative regulation of interleukin-12 production; negative regulation of T cell activation; negative regulation of T-helper 1 cell differentiation; negative regulation of thymocyte apoptotic process; regulation of apoptotic process; regulation of receptor signaling pathway via JAK-STAT; regulation of T cell apoptotic process; response to interleukin-15; and 6 more
Cellular component: extrinsic component of cytoplasmic side of plasma membrane; cytoplasmic side of plasma membrane; cytosol; endosome; extrinsic component of plasma membrane; plasma membrane; cytoplasm; endomembrane system; membrane
Genetic constraint (gnomAD): Loss-of-function variants: 88 observed, 112.58 expected, observed/expected ratio (o/e) 0.78, 90% interval 0.66 to 0.93. The upper end of that interval is the gene's LOEUF score, 0.93, which puts it in group 3 of 6, group 1 being the genes least tolerant of losing a copy. Missense variants: 1,253 observed, 1,426.6 expected, observed/expected ratio (o/e) 0.88, 90% interval 0.84 to 0.92. Synonymous variants: 592 observed, 595.06 expected, observed/expected ratio (o/e) 0.99, 90% interval 0.93 to 1.07.
Gene-disease validity (ClinGen):
ClinGen rates the evidence that JAK3 causes each of these diseases.
T-B+ severe combined immunodeficiency due to JAK3 deficiency (autosomal recessive): Definitive. Severe combined immunodeficiency (SCID) T-B+ due to JAK3 deficiency is a form of SCID characterized by severe and recurrent infections, associated with diarrhea and failure to thrive.
Cancer hallmarks: proliferative signalling (promotes)
Homologues: Orthologues: chimpanzee JAK3 (99% identical), pig JAK3 (91% identical), dog JAK3 (89% identical), mouse Jak3 (82% identical), rat Jak3 (81% identical), guinea pig JAK3 (76% identical), macaque JAK3 (52% identical). Paralogues in human: JAK2 (49% identical), JAK1 (40% identical), TYK2 (40% identical), BLK (15% identical), FES (15% identical), PTK2 (15% identical), ABL1 (14% identical), ABL2 (14% identical), TEC (14% identical), FYN (14% identical), HCK (14% identical), LYN (14% identical), and 20 more.
Diseases named in the same sentence as JAK3 in open-access papers:
JAK3 is named in the same sentence as 289 diseases in open-access papers, as found by Europe PMC text mining. Sharing a sentence is not in itself a finding about the gene and the disease. The quoted sentences say what the papers report.
rheumatoid arthritis (67 papers, 2008 to 2026). A chronic, systemic autoimmune disorder characterized by inflammation in the synovial membranes and articular surfaces. "For example, tofacitinib, a potent Janus-associated kinase (JAK) 1 and JAK3 antagonist developed by Pfizer, reduced signs and symptoms of rheumatoid arthritis (RA) and improved physical function of patients with RA." (PMID 33530480, 2021). "An up-regulation of JAK3 has been on the contrary associated with rheumatoid arthritis both in animals and in humans; for these reasons, JAK3 represents a good target for immunotherapy in severe autoimmune disorders." (PMID 24416411, 2014). "However, compounds L21 and L46 demonstrated stable performance, suggesting their effectiveness in treating rheumatoid arthritis and other autoimmune conditions associated with JAK3 inhibition." (PMID 39189018, 2024). "JAK3 deficiency is significantly correlated with a multitude of immune-associated disorders, includes tuberculosis, severe combination immunodeficiency, and rheumatoid arthritis, with a score>0.5." (PMID 35844366, 2022). "The potential for CP-690550 to attenuate multiple cytokines associated with rheumatoid arthritis by virtue of its ability to inhibit JAK3 may provide improved efficacy vs a single agent." (PMID 18234077, 2008). "Inhibiting JAK3 reduces the production of pro-inflammatory cytokines such as interleukin-6 and interleukin-17, which are two important cytokines in rheumatoid arthritis." (PMID 39189018, 2024). "Tofacitinib is an oral JAK-1 and JAK-3 inhibitor that has been approved for the treatment of rheumatoid arthritis and ulcerative colitis, plaque psoriasis, atopic dermatitis, vitiligo, and alopecia areata." (PMID 38397117, 2024). "It is an oral inhibitor of the enzymes JAK1, JAK2, and JAK3, which was approved in 2012 for the treatment of moderate to severe rheumatoid arthritis (RA)." (PMID 39770590, 2024). "JAK3 inhibitors have demonstrated significant efficacy in treating rheumatoid arthritis by reducing inflammation and symptoms." (PMID 38516192, 2024). "JAK3 inhibitors have shown great success in treating rheumatoid arthritis, decreasing inflammation and symptoms." (PMID 39189018, 2024). "Inhibitors of these kinases are under consideration for treatment of immune disorders, and one inhibitor of JAK3, tofacitinib, is in clinical use for treatment of rheumatoid arthritis." (PMID 36827099, 2023). "Tofacitinib is a selective inhibitor of JAK3 that is used to treat certain autoimmune diseases, including rheumatoid arthritis, which helps reduce the activity of the immune system." (PMID 38202604, 2023). "This work aimed to find new inhibitors of the CYP3A4 and JAK3 enzymes, which are significant players in autoimmune diseases such as rheumatoid arthritis." (PMID 38202604, 2023). "Ritlecitinib, an irreversible JAK3 and tyrosine kinase inhibitor, is currently used for the treatment of rheumatoid arthritis." (PMID 36902341, 2023). "Tofacitinib works very well to treat rheumatoid arthritis by blocking JAK3, a vital regulator of immune cell differentiation and proliferation." (PMID 37570884, 2023). "The results of these analyses suggest that the newly predicted molecules have promising potential as JAK3 inhibitors for the treatment of rheumatoid arthritis." (PMID 37570884, 2023). "Tofacitinib (Xeljanz®) is a potent, selective JAK inhibitor that preferentially inhibits JAK1 and JAK3 used for the treatment of moderate to severe active rheumatoid arthritis (RA), Tofacitinib had promising in vitro activity on MM cells." (PMID 36311273, 2022). "Several JAK inhibitors are under investigation for the treatment of hematopoietic diseases, including myeloproliferative neoplasms and autoimmune diseases, including the JAK3-specific Tofacitinib for treatment of rheumatoid arthritis." (PMID 35622134, 2022). "On the other hand, the JAK3 inhibitor, decernotinib also showed a high potential activity in the treatment of rheumatoid arthritis." (PMID 35631587, 2022).
rheumatoid arthritis (continued). "Further, miR-221-3p drives M2 macrophages to a pro-inflammatory function by directly targeting JAK3 in rheumatoid arthritis." (PMID 35898875, 2022). "In the same year, the U.S. Food and Drug Administration (FDA) approved a second JAK inhibitor: tofacitinib (JAK1 and JAK3) for the treatment of rheumatoid arthritis." (PMID 34532638, 2021). "Tofacitinib is already approved as a JAK1 and JAK3 inhibitor for the treatment of rheumatoid arthritis, psoriatic arthritis, and ulcerative colitis." (PMID 34532638, 2021). "A selective Jak3 inhibitor CP-690550 (Xeljanz) approved by the FDA for certain chronic inflammatory conditions demonstrates immunosuppressive activity in rheumatoid arthritis, psoriasis, and organ transplant rejection." (PMID 33814980, 2021). "Tofacitinib (TOF) inhibits JAK1/JAK3 and has been proven effective in rheumatoid arthritis (RA), psoriatic arthritis, ulcerative colitis, and a new therapeutic option in systemic lupus." (PMID 34313812, 2021). "USRE41783E (Reissue of US6627754B2) provides pyrrolo[2,3-d]pyrimidines as JAK3 inhibitors to treat rheumatoid arthritis, psoriasis, cancer, and leukemia." (PMID 34451807, 2021). "Tofacitinib (Xeljanz®, Pfizer) was approved by the USFDA as a JAK3-selective suppressor for rheumatoid arthritis (RA) therapy in year 2012 and recently approved to treat Ulcerative Colitis." (PMID 30847297, 2019). "CP-690550 is a JAK3 inhibitor that is currently in clinical trials for treatment of rheumatoid arthritis, juvenile idiopathic arthritis, ulcerative colitis and other inflammatory conditions." (PMID 28839214, 2017). "JAK1 inhibitors, for example, small molecule tofacitinib that inhibits JAK1 and JAK3, are used for treatment of rheumatoid arthritis and are currently tested in other immunological disorders, such as psoriasis and inflammatory bowel disease." (PMID 28008925, 2016). "Inhibition of JAK3 has been explored as an alternative therapy to cyclosporine in transplant rejection and in treatment of rheumatoid arthritis, psoriasis, ulcerative colitis, Crohn’s disease, and dry eye syndrome." (PMID 22916261, 2012). "Phase I and II clinical trials proved efficacy and safety of JAK3 inhibition in preventing transplant rejection and eliminating the symptoms of rheumatoid arthritis and psoriasis." (PMID 22359619, 2012). "CP690,550, a JAK3 inhibitor that is currently in clinical trials, has been shown to significantly reduce joint inflammation in rheumatoid arthritis (RA)." (PMID 21884580, 2011). "Therefore, in the pursuit of isoform selectivity, several JAK3 selective inhibitors have been reported for the treatment of rheumatoid arthritis, psoriasis, etc.." (PMID 38637842, 2024). "JAK3 inhibitors, in particular, have been demonstrated to decrease the production of pro-inflammatory cytokines, such as IL-2, IL-6 and IL-17, all of which contribute to the pathophysiology of rheumatoid arthritis." (PMID 37570884, 2023). "In addition, a phase 2/3 study is underway to assess the safety and long-term efficacy of the JAK3 inhibitor VX-509427–429 in rheumatoid arthritis patients (NCT01830985)." (PMID 36797236, 2023). "A systematic review and meta-analysis evaluating the results of more than 4000 patients using JAK3 inhibitors for the treatment of rheumatoid arthritis concluded that the treated group showed significant improvement in signs and symptoms compared to other groups." (PMID 37373437, 2023). "The JAK3 antagonist CP-690550 showed potential benefits in the treatment of rheumatoid arthritis." (PMID 38139216, 2023). "In addition, several JAK3 selective inhibitors have been evaluated for their efficacy in the treatment of rheumatoid arthritis." (PMID 35631587, 2022). "The story of JAK3 selective inhibitors started after the development of Tofacitinib – a pan-JAK inhibitor that was the first FDA-approved JAK inhibitor for the treatment of RA (rheumatoid arthritis)." (PMID 32528970, 2020).
rheumatoid arthritis (continued). "The baseline risk of HZ in rheumatoid arthritis is 1.5–2-fold higher compared to the general population, and the incidence of HZ reported with tofacitinib, which preferentially inhibits JAK1, JAK2, and JAK3, is double that reported in RA." (PMID 32974356, 2020). "Drugs targeting JAK3 in the treatment of Rheumatoid arthritis is relevant." (PMID 31435152, 2019). "Two long term extension studies of tofacitinib, (a JAK1/JAK3 inhibitor with a nearly identical target profile to that of oclacitinib), in patients with rheumatoid arthritis found that fewer than 5% experienced neutropenia of any degree, and most were mild in severity." (PMID 31409327, 2019). "Tofacitinib, a JAK3 inhibitor approved for clinical use in rheumatoid arthritis, is particularly interesting as it possesses considerable specificity across the kinome: In a 317 kinase panel, tofacitinib only inhibits 3 kinases with an IC50 <500 nM: JAK3, JAK2 and PRK1." (PMID 25111382, 2014). "Several small molecule Jak3 inhibitors have been developed and are undergoing clinical evaluation for inflammatory conditions such as rheumatoid arthritis, psoriasis and several autoimmune conditions including autoimmune encephalitis, and rejection of organ transplants." (PMID 22363534, 2012). "For example, tofacitinib, a JAK3-specific inhibitor, is used to treat ankylosing spondylitis (AS), rheumatoid arthritis (RA), psoriasis, psoriatic arthritis, ulcerative colitis, polyarticular juvenile idiopathic arthritis, etc.." (PMID 37122731, 2023). "We also demonstrated that tasocitinib, a JAK3 inhibitor used clinically to treat rheumatoid arthritis (RA) and Crohn’s disease (CD), can reduce neuroinflammation and increase survival of Jak3−/+ heterozygotes in the ECM model." (PMID 25268389, 2014). "Of the four subtypes of the JAK family (JAK1, JAK2, JAK3, and TYK2), JAK1 is involved in signaling through inflammatory cytokines such as IL-6, and it is known to cause lymphocyte activation and proliferation in rheumatoid arthritis (RA)." (PMID 39944226, 2025). "Tofacitinib, which primarily inhibits JAK1 and JAK3 with partial JAK2 inhibition, is approved for conditions like rheumatoid arthritis (RA) and ulcerative colitis (UC), but has emerging applications in dermatologic diseases." (PMID 41235382, 2025). "The Janus kinase 3 (JAK3) family, particularly JAK3, is pivotal in initiating autoimmune diseases such as rheumatoid arthritis." (PMID 39189018, 2024). "Corresponding proteins from many of these DEGs have already been identified as drug targets for the treatment of various diseases such as COVID-19, asthma or rheumatoid arthritis (e.g., CCR2, CCR3, CXCL8, JAK3, HRH, CA4, see clinicaltrials.gov)." (PMID 38242945, 2024). "Inhibiting JAK3 or JAK1 decreases the production of pro-inflammatory cytokines such as interleukin-6 and interleukin IL-17, two key cytokines in rheumatoid arthritis." (PMID 38516192, 2024). "Tofacitinib is used against rheumatoid arthritis and other inflammatory diseases and mainly targets JAK1 and JAK3, with a lesser effect on JAK2." (PMID 36979068, 2023). "Tofacitinib (Xeljanz®, Pfizer, New York, NY, USA) is another JAK inhibitor that selectively targets JAK3, which was approved by the USFDA in 2012 for the treatment of rheumatoid arthritis and more recently for the treatment of ulcerative colitis." (PMID 36232600, 2022). "Tofacitinib, with specificity for JAK1 and JAK3, reduces IL-23 triggered IL-17A secretion from T cells of rheumatoid arthritis (RA) and psoriatric arthritis (PSA) patients in vitro, and was the first JAK inhibitor to be licensed for treatment of RA in the United States15,16." (PMID 30353145, 2018). "Tofacitinib is a potent inhibitor of JAK1 and JAK3 and currently approved for the treatment of rheumatoid arthritis (RA), has demonstrated effectiveness in the treatment of psoriasis in phase III clinical trials, and is currently tested as immunomodulator for organ transplantation." (PMID 26983628, 2016).
rheumatoid arthritis (continued). "CP-690550 which has a similar structure to the JAK3 inhibitor VI used in our study, is currently undergoing Phase III study in patients with active rheumatoid arthritis." (PMID 22359619, 2012). "It is proposed that the ability of YSTB to slow the progression of rheumatoid arthritis may be related to modulating the JAK/STAT pathway by degrading the phosphorylated expression of JAK2, JAK3, and STAT3 proteins, whereas elevated SOCS3 protein expression." (PMID 38966637, 2024). "Tofacitinib, which inhibits JAK1, JAK3, and to a slightly lesser extent JAK2, therefore may function to reduce or inhibit inflammatory pathways that lead to rheumatoid nodule formation." (PMID 39070924, 2024). "A JAK3 inhibitor was approved by the FDA as a therapeutic strategy for rheumatoid arthritis as an alternative for patients who do not respond well to other drugs." (PMID 37373437, 2023). "The new JAK3 inhibitor, CP690,550, has shown efficacy in the treatment of rheumatoid arthritis." (PMID 21884580, 2011). "Currently, no selective JAK3 inhibitor is available for rheumatoid arthritis." (PMID 42050339, 2026). "JAK3 is a main tyrosine kinase within the JAK kinase family, whose inhibition plays a crucial role in the treatment of rheumatoid arthritis (RA)." (PMID 42050339, 2026). "On the other hand, Tofacitinib inhibits JAK1, JAK2, JAK3 and is approved by the Food and Drug Administration (FDA) for treating rheumatoid arthritis (RA), psoriatic arthritis and ulcerative colitis." (PMID 38920670, 2024).